TFE3 (transcription factor binding to IGHM enhancer 3)
Diseases named in the same sentence as TFE3 in open-access papers (continued):
Sharing a sentence is not in itself a finding about the gene and the disease.
cancer (continued). "GPNMB is overexpressed in a number of cancer types and was first shown to be transcriptionally regulated by MITF, but subsequently was identified as a direct transcriptional target of TFE3 and is highly expressed in TFE3-fusion RCC." (PMID 37095531, 2023). "The TFE3 fusion protein can also accelerate the mitochondrial generation and energy production by activating the PGC-1α and NRF1 pathways, thereby providing more energy for the proliferation of cancer cells." (PMID 36906611, 2023). "In addition, a feedback loop has been proposed in which overexpression of TFEB, TFE3, or MITF upregulates RagD GTPase resulting in hyperactivation of mTORC1, induction of cellular proliferation, and cancer growth." (PMID 33490073, 2020). "Our methods can facilitate TFE3-RCC diagnosis based on routinely collected H&E-stained histopathology slides, thereby contributing to accurate sample curation and treatment development of this rare and aggressive cancer subtype." (PMID 32286325, 2020). "Studies have shown that the 5-year cancer-specific survival rate for TFE3-positive patients was 15.6% as compared to 87.5% for TFE3-negative patients." (PMID 24455396, 2013). "We performed immunostaining for transcription factor E3 (TFE3), human melanoma black 45 (HMB45), melan-A, desmin, pan-cytokeratin (CK), paired box 8 (PAX8), CD10, hormone receptors, and S100, and targeted RNA and DNA sequencing using commercially available cancer gene panel." (PMID 35626258, 2022). "Our finding that TFE3 further accumulates in the nucleus of cancer cells lacking NMT1, LAMTOR1, or in cells treated with NMTi is consistent with both the inhibition of mTORC1 activity by NMTi, and the autophagy blockade provoked by the lack of degradative lysosomal activity." (PMID 32686708, 2020). "A recent clinical study suggested that cancer-specific survival differed significantly between adult patients with positive TFE3 rearrangement RCCs and adult patients with negative TFE3 rearrangement PRCC, which implied that adult RCCs with TFE3 rearrangement may be a clinically aggressive tumour." (PMID 32042048, 2020). "Of note, although TFEB and TFE3 seem to have a proapoptotic action upon treatment with etoposide, the overexpression of TFEB in cancer cells in the presence or absence of genotoxic agents appears to promote cell survival." (PMID 33490073, 2020). "Some of the shared genomic features, such as gene fusions involving TFE3 or TFEB, are present in approximately 10% of samples and show no particular disposition to type I or type II cancers." (PMID 30099580, 2018). "Moreover, our results show that DT-061 modulation of PP2A regulates TFE3 to promote ATF4 expression and activity in both cancer and non-malignant cells, albeit distinctive downstream response mechanisms are activated, resulting in two distinct outcomes." (PMID 39349971, 2024). "The therapeutic potential of ERBB3 inhibitors, such as AZD8931, demonstrates that TFE3-RCC cells lacking ARID2 are more sensitive to this treatment, providing promising directions for improving outcomes for patients with this aggressive cancer subtype." (PMID 39727945, 2024).
infection (13 papers, 2018 to 2025). The state of being infected such as from the introduction of a foreign agent such as serum, vaccine, antigenic substance or organism. "On the other hand, TFEB as well as TFE3 have been observed to be activated during infection and double-deficiency was consistently observed to yield smaller CCVs." (PMID 40435199, 2025). "TFE3, a member of the basic helix-loop helix leucine zipper (bHLH-LZ) transcription factor family, is implicated in various cellular processes, including cell starvation, ER stress, mitochondrial damage, pathogen infection, lysosomal stress, and Golgi apparatus stress." (PMID 39652582, 2024). "As before, we did not observe any significant differences in Salmonella survival at 4 h post-infection that were dependent on TFEB/TFE3 and growth-phase of the bacteria." (PMID 38051049, 2024). "To assess TFE3 nuclear translocation, we infected macrophages with wild-type or ΔEhaF EHEC and analyzed the localization of TFE3 in the nucleus at multiple time points of infection by confocal microscopy." (PMID 37041208, 2023). "Strikingly, TANK phosphorylation upon EHEC and ΔEhaF infection was greatly reduced in Tfe3−/− cells indicating that TFE3 is essential for TANK phosphorylation." (PMID 37041208, 2023). "Strikingly, compared to EHEC infection-induced low and delayed TFE3 nuclear translocation, ΔEhaF infection resulted in a faster and markedly higher levels of TFE3 in the nucleus." (PMID 37041208, 2023). "The roles of TFEB and TFE3 in lysosomal regulation for cellular adaptation under a variety of acute stress conditions such as nutrient deprivation and pathogen infection are well documented." (PMID 33932147, 2021). "TFE3 nuclear translocation is regulated by several signals including mTORC1, ER stress, mitochondrial damage, and pathogen infection." (PMID 30849994, 2019). "Other stressors, such as ER stress, pathogen infection and oxidative stress, result in TFE3 and TFEB activation despite high mTORC1 activity." (PMID 30520728, 2018). "Some viruses may benefit from inducing TFEB and TFE3 activation at early infection times as a way to prevent cell death and enhance production of autophagosomal membranes that they require for replication." (PMID 40195022, 2025). "The transcription factors TFEB and TFE3 translocate from the cytosol to the nucleus in response to a wide variety of stress conditions, including nutrient deprivation, organelle damage, oxidative stress, and pathogen infection." (PMID 40195022, 2025). "However, this difference between infection with stationary or late-log Salmonella remained when the host cells were mutated for TFEB and/or TFE3." (PMID 38051049, 2024). "Importantly, TFE3 mRNA levels significantly increased at 12-, 24-, 36-, and 48- hours post-AIV infection, with a subsequent decrease in TFE3 protein levels observed at 36- and 48-hours post-infection compared to mock-infected cells." (PMID 39652582, 2024). "All these strains induced TFE3 nuclear translocation at 36 hours post-infection." (PMID 39652582, 2024). "The results showed that TFE3 shRNA infection effectively down-regulated TFE3 at protein level." (PMID 39695174, 2024). "Additionally, mRNA levels of pro-inflammatory cytokines including IL-6, TNF-α, IL-1β, and IL-8 were significantly reduced in BALB/cTFE3-/- mice relative to BALB/cTFE3+/+ mice, suggesting a critical role of TFE3 in viral replication and infection." (PMID 39652582, 2024). "Furthermore, TFE3 nuclear translocation was assessed following infection with other subtype influenza viruses (A/California/04/09 (CA04, H1N1), A/Puerto Rico/8/1934 (PR8, H1N1), A/chicken/Taixing/10/2010 (TX, H9N2), and A/Chicken/Guangdong/04/2017 (GD, H7N9))." (PMID 39652582, 2024). "Editing of these genes, including those encoding CTSL, cholesterol transporters NPC1/2, WDR81/91, and TFE3, markedly reduced infection, suggesting that Sdel and SARS-CoV may utilize similar entry machinery in this cell type." (PMID 33574281, 2021).
infection (continued). "The functional effect of IBV infection on TFEB/TFE3 was first assessed by isolating cytoplasmic and nuclear proteins from IBV-infected HeLa cells at different time points post-infection." (PMID 41450945, 2025). "The specific contribution of TFEB, TFE3, MITF, and their temporal regulation during infection requires further investigation." (PMID 40435199, 2025). "In this study, infection of TFEB- and TFE3-knockdown cells with IBV, HCoV-OC43 and PEDV showed down-regulation of the pro-apoptotic factor CHOP and autophagy-related gene SQSTM1." (PMID 41450945, 2025). "Among the analyzed GAS response pathways, TFE3 was significantly activated during AIV infection, while HSP47 was activated early in the infection process, and CREB3-ARF4 remained inactive." (PMID 39652582, 2024). "Interestingly, two teams recently reported that AMPK could dephosphorylate TFEB/TFE3, induce their nuclear localization independently of mTOR activity, and activate TFEB/TFE3 boost the expression of lysosomal and inflammatory genes in macrophages in response to infection." (PMID 33330475, 2020). "At later infection times, however, TFEB and TFE3 degradation or inactivation may avert autophagy-mediated clearance of assembled viral particles and even facilitate virus dissemination by inducing cell death." (PMID 40195022, 2025). "Interestingly, EHEC, but not ΔEhaF, infection, resulted in a reduction in TFE3 protein levels at the early stages of infection, however, this decrease was less discernable in the subsequent stages." (PMID 37041208, 2023).
kidney (3 papers, 2014 to 2025). "On the other hand, as a pivotal transcription factor for autophagy-lysosome genes, TFE3 activation due to gene fusion also notably causes kidney malignancy." (PMID 36935008, 2023).
genetic disease (2 papers, 2015 to 2024). "In Birt-Hogg-Dubé (BHD) syndrome, which is a rare genetic disease caused by mutations in the folliculin (FLCN) gene, renal cystic epithelial cells exhibit increased nuclear localization of AGS11/TFE3." (PMID 26300785, 2015). "In the future, models of genetic disorders associated with post-Golgi trafficking inhibition need to be established to further elucidate the pathophysiological role of Golgi-LC3 lipidation and TFE3." (PMID 39284911, 2024).
kidney disease (2 papers, 2024). "The other members of the TFEB family (TFE3, MITF, and TFEC) may impact TSC-associated kidney disease and other manifestations of TSC, via similar mechanisms." (PMID 38195686, 2024).
metabolic disease (2 papers, 2016 to 2023). A congenital disorder (due to inherited enzyme abnormality) or acquired (due to failure of a metabolically important organ) disorder resulting from an abnormal metabolic process. "For metabolic disorders caused by insufficient insulin function, it may be possible to use a method that directly or indirectly improves TFE3 activity to assist in the treatment of such disorders." (PMID 36906611, 2023). "This also suggests that indirectly or directly increasing TFE3 content by recombinant human TGF-β1 or by adenovirus expressing human TFE3 may delay the progression of metabolic diseases caused by the lack of traditional mitochondrial autophagy." (PMID 36906611, 2023). "Therefore, TFE3 may provide a novel therapeutic strategy for the treatment of NAFLD and other metabolic diseases." (PMID 26999124, 2016).
neurodegenerative disease (2 papers, 2021). A disorder of the central nervous system characterized by gradual and progressive loss of neural tissue and neurologic function. "We conclude that the VPS41 variants specifically abrogate HOPS function, which interferes with the TFEB/TFE3 axis of mTORC1 signaling, and cause a neurodegenerative disease." (PMID 33851776, 2021). "Efforts have been made to develop TFEB agonists to enhance autophagy in neurodegenerative disease, and our results suggest that TFE3 could also be a promising drug target." (PMID 34912803, 2021).
adenocarcinoma (1 paper, 2025). A common cancer characterized by the presence of malignant glandular cells. "Immunohistochemically, adenocarcinoma expresses epithelial markers such as CK and EMA, but negative for CD31, CD34 and especially CAMTA1 and TFE3." (PMID 40040722, 2025). "Genetically, CAMTA1 or TFE3-rearrangement is present in EHE, but not in poorly differentiated adenocarcinomas." (PMID 40040722, 2025).
immune dysfunction (1 paper, 2024). "We highlight TFEB and TFE3 as a potential therapeutic target to regulate the ALP and immune dysfunction in DCs caused by As exposure." (PMID 38267572, 2024). "In summary, our study confirmed that TFEB and TFE3 activated ALP and therefore may exert a collaboratively protective effect on As-induced immune dysfunction in DCs." (PMID 38267572, 2024).
TFE3 also shares sentences with these, for which no sentence is quoted: adrenocortical carcinoma (4 papers); Parkinson disease (4); alveolar rhabdomyosarcoma (3); clear cell sarcoma (3); hemangioendothelioma (3); oncocytic tumour (3); cardiomyopathy (2); colorectal cancer (2); dermatofibrosarcoma protuberans (2); epithelioid hemangioma (2); epithelioid sarcoma (2); fibromyxoid neoplasm (2); oncocytoma (2); ossifying fibromyxoid tumor (2); renal failure (2); renal medullary carcinoma (2); adenopathy (1); anaplastic large cell lymphoma (1); avian influenza (1); Bartonella infection (1); bile duct carcinoma (1); Birt-Hogg-Dube syndrome (1); bone metastasis (1); cervical cancer (1); cervical squamous cell carcinoma (1); chronic myeloid leukemia (1); chronic rhinosinusitis (1); Cognitive impairment (1); COVID-19 (1); cyst (1).
A further 64 diseases each share a sentence with TFE3 in 1 paper.